RAB14 (RAB14, member RAS oncogene family)
Diseases named in the same sentence as RAB14 in open-access papers (continued):
Sharing a sentence is not in itself a finding about the gene and the disease.
infection (12 papers, 2010 to 2024). The state of being infected such as from the introduction of a foreign agent such as serum, vaccine, antigenic substance or organism. "Further research is necessary to fully characterize chlamydial proteins involved in the manipulation of Akt/AS160/Rab14 cascade in order to design specific targeted molecular therapies to control infections caused by this widespread intracellular pathogen." (PMID 31001235, 2019). "Time course analysis revealed that Rab14 associated with inclusions by 10 h post infection and was maintained throughout the entire developmental cycle." (PMID 21124879, 2010). "However, although Rab14 presented dispersedly at the early stage (4h p.i.)of both infection states, Rab14 recruitment became associated to the inclusions and delimited the border of inclusions as the infection was processed." (PMID 34169005, 2021). "Interestingly, while Rab11/Rab14 remained associated with the C. pneumoniae inclusion membrane from internalization throughout the whole infection cycle, Rab4, like Rab7, is lost from 30 min onwards." (PMID 28787457, 2017). "Similarly, it has been reported that some Rab14 association was observed around Chlamydia-modified phagosomal inclusions at later stages of infection." (PMID 25644001, 2015). "The strongest recruitment was observed with Rab14, in which the peripheral distribution of Rab14-positive vesicles was modified after the infection and accumulated mostly around the chlamydial inclusion." (PMID 33936099, 2021). "In the case of Chlamydia, several Rab proteins, e.g. Rab4, Rab10, Rab11 or Rab14, are known to interact with the mature chlamydial inclusion membrane from 2 h post infection (hpi) onwards." (PMID 28787457, 2017). "Here we have combined live-cell imaging with genetic manipulation of host macrophages to study the dynamic role of Rab14 in phagosome maturation during infection by C. albicans." (PMID 25644001, 2015). "Thus, Fip2 is essential for internalization and infection, and is found on the nascent inclusion, where it colocalizes with Rab11/Rab14." (PMID 28787457, 2017). "Furthermore, we show that the Rab11/ Rab14 adaptor protein Rab11-Fip2 (Fip2) is recruited to the nascent inclusion upon internalization and retained in the membrane throughout infection." (PMID 28787457, 2017). "It is conceivable that during infection, the primary uptake of Plasmodium-parasitized erythrocytes by macrophages would increase the levels of Rab14 and thereby inhibit subsequent phagocytic activity of the macrophages, decreasing host-mediated parasite clearance." (PMID 22911692, 2012). "This is suggested by the observation that Rab14 and Rab9a, whose expression is upregulated upon infection with P. berghei and E. coli or S. enterica, respectively, are negative regulators of the phagocytosis of these microorganisms, since their silencing leads to an increase in phagocytosis." (PMID 22911692, 2012). "We also attempted to analyze the protein levels of Rab9a and Rab14 upon infection." (PMID 22911692, 2012). "To determine whether there was a difference in Rab14 recruitment between persistent infection and acute infection during the developmental cycle, we detected the intracellular distribution of endogenous Rab14 in cells of two infection states, at different post-infection times." (PMID 34169005, 2021).
bacterial infection (2 papers, 2012 to 2024). "Galectin-8 binding partners were identified in murine macrophages during intracellular bacterial infection by IP-LC/MS, including autophagy-related proteins such as TAX1BP1 and ubiquitin, and lysosomal proteins and membrane trafficking proteins, including Rab7 and Rab14." (PMID 38395460, 2024). "Since the expression of Rab14 is not upregulated in bacterial infections, we hypothesized that this Rab would not play any role in phagocytosis of the bacteria studied." (PMID 22911692, 2012).
RAB14 also shares sentences with these, for which no sentence is quoted: prostate carcinoma (2 papers); renal carcinoma (2); respiratory disease (2); Alzheimer disease (1); breast tumor (1); esophageal tumor (1); gastric tumors (1); glioblastoma (1); glioma (1); invasive carcinoma (1); liver cancer (1); lung squamous cell carcinoma (1); malignant mesothelioma (1); nasopharyngeal carcinoma (1); neuroblastoma (1); Parkinson disease 7 (1); postmenopausal osteoporosis (1); preeclampsia (1); renal cell carcinoma (1); triple-negative breast carcinoma (1).